HOXA9 (homeobox A9)
Diseases named in the same sentence as HOXA9 in open-access papers (continued):
Sharing a sentence is not in itself a finding about the gene and the disease.
glioma (continued). "Therefore, BMPER, CXCL10, and HOXA9 can be used as novel targets for antiangiogenic treatment of primary high-grade gliomas." (PMID 32432046, 2020). "Transcriptome sequencing results confirmed that the expression levels of BMPER, CXCL10, and HOXA9 in the cases that could form orthotopic xenograft glioma models were significantly higher than those in the cases that could not form xenografts." (PMID 32432046, 2020). "Interestingly, it was recently reported that HOXA genes are part of a gene‐signature characteristic of WNT‐dependent glioma stem cells, which fits well with our data linking HOXA9 and WNT6 in GBM." (PMID 31923345, 2020). "Interestingly, this novel molecular link between WNT6 and HOXA9 was not limited to glioma, as they were co‐expressed also in patients with other tumor types." (PMID 31923345, 2020). "It has also been reported that miR-638 targets HOXA9 3’UTR directly, downregulates HOXA9 expression, and thus inhibits the two Wnt signaling effectors c-Myc and Cyclin D1, while overexpression of HOXA9 can partially abolish the miR-638 effects in glioma." (PMID 33154193, 2020). "Similarly, significant correlations between HOTAIR and HOXA9 expression were also observed in specific combinations of glioma grades (Portuguese dataset WHO grades II+III, III, III+IV and II+III+IV; French dataset IDH-wt WHO grade III and grade IV)." (PMID 29644006, 2018). "Previous observations from our group suggested HOXA9 as a possible regulator of HOTAIR in glioma." (PMID 29644006, 2018). "Importantly, HOTAIR was frequently co-expressed with HOXA9 in high-grade gliomas from TCGA, Oncomine, and our Portuguese and French datasets." (PMID 29644006, 2018). "High expression levels of HOXA9 were also predictive of shorter survival in glioma patient samples." (PMID 28969042, 2017). "The endogenous expression levels of HOXA9 in a panel of glioma cell lines was evaluated by qPCR." (PMID 25762636, 2015). "In conclusion, our study establishes HOXA9 as a critical oncogene in the initiation and progression of glioma, and provides evidences into the mechanisms by which patients with HOXA9-positive GBMs respond poorly to temozolomide and have worse clinical outcomes." (PMID 25762636, 2015). "Additionally, miR-638 directly targets the HOXA9 3’UTR, suppresses HOXA9 expression, and inhibits the two Wnt signaling effectors c-Myc and Cyclin D1, whereas overexpression of HOXA9 can partially counteract the effects of miR-638 in glioma." (PMID 35883576, 2022). "HOXA9 was found to be highly overexpressed in a subset of GBM patients comparing to lower grades glioma (LGG, WHO grades II/III) patients and normal controls, confirming that HOXA9 is associated with glioma grade and may be important in tumor progression." (PMID 25762636, 2015). "In summary, in primary high-grade gliomas, BMPER, CXCL10, and HOXA9 expression can promote early-phase tumor growth and further progression by increasing tumor neovascularization." (PMID 32432046, 2020). "In various cohorts of glioma patients, mRNA levels of WNT6 and HOXA9 were significantly correlated, extending our in vitro and in vivo findings into the clinical setting." (PMID 31923345, 2020). "By integrating in vitro and in vivo models, and data from patients, this study unravels a novel molecular link between the homeobox HOXA9 gene and WNT6 in glioma, which has prognostic relevance in patients with highly aggressive GBMs." (PMID 31923345, 2020). "Many reports have identified HOXA9 and HOXA10 signatures in GBM, and high expression levels of HOXA9 and HOXA10 were predictive of shorter survival in some high-grade glioma patients." (PMID 26356815, 2015). "Accordingly, HOXA9 and HOXA11 expression also increased from lower-grade glioma to high-grade glioma." (PMID 26356815, 2015).
glioma (continued). "In the present study, we first analyzed the expression of HOXA9, HOXA10, HOXA11, and HOXA13 protein in glioma tissues; we then further analyzed the expression of HOXA9, HOXA10, HOXA11, HOXA13, and HOTTIP mRNA in the same samples." (PMID 26356815, 2015). "By western-blot analysis, HOXA9, HOXA11, and HOXA13 were dramatically up-regulated in GBM, and HOXA10 merely showed a slight increase in high-grade glioma." (PMID 26356815, 2015). "In this report, we pinpoint the genome-wide transcriptome of HOXA9 in GBM and demonstrate its functional relevance in initiating gliomas in vivo using immortalized astrocytes and established GBM cells." (PMID 25762636, 2015). "In the two glioma surgical specimen groups, the expression levels of BMPER, CXCL10 and HOXA9 in the surgical specimens that could form xenografts were significantly higher than those in the surgical specimens that could not form xenografts." (PMID 32432046, 2020). "Specifically, high expression of HOXA9 and HOXA10 have been reported in human glioma cell lines." (PMID 31073965, 2019). "Taken together, our results strongly suggest that HOTAIR and HOXA9 are concomitantly co-expressed in human gliomas, but not in other cancer types." (PMID 29644006, 2018). "Strikingly, while HOXA9-negative hTERT/E6/E7 cells did not form tumors, the expression of HOXA9 in hTERT/E6/E7 rendered these cells highly tumorigenic in the brain, accompanied by glioma-related symptomatology and death." (PMID 25762636, 2015). "Together, these results suggest that gene amplification or methylation are not major drivers of HOXA9 overexpression in glioma." (PMID 25762636, 2015). "Similarly, and as previously proposed, a read‐through transcript of HOXA10 and HOXA9 might account for the detected HOXA9 transcription signal because the canonical CGI/promoter of this gene was DNA‐methylated and H3K4me3‐depleted in IDHwt glioma samples." (PMID 33720519, 2021). "Strikingly, we also showed that hTERT/E6/E7 immortalized astrocytes that overexpress HOXA9 are able to originate orthotopic gliomas in vivo, in contrast to HOXA9-negative hTERT/E6/E7 cells, which may partly be explained by the notion that tumor-initiating cells have high stem cell potential." (PMID 25762636, 2015).
non-small cell lung carcinoma (19 papers, 2016 to 2025). A group of at least three distinct histological types of lung cancer, including non-small cell squamous cell carcinoma, adenocarcinoma, and large cell carcinoma. "We aimed to evaluate NKA and methylation of the HOXA9 promoter region as prognostic biomarkers in patients with advanced non-small cell lung cancer treated with PD-1/PD-L1 inhibitors." (PMID 37137997, 2023). "One study reported that miR-196b directly targeted HOXA9 adjusting aggressiveness through NF-κB activity in non-small cell lung cancer cells." (PMID 33611311, 2021). "Previously, we showed that HOXA9 can serve as a potential therapeutic target for the treatment of metastatic non-small cell lung cancer (NSCLC)." (PMID 33238593, 2020). "Promoter hypermethylation of HOXA9 was found in oral, breast, ovarian, bladder, and non-small cell lung cancer in which HOXA9 functions as a tumor suppressor gene." (PMID 30832707, 2019). "Downregulation of HOXA9 was suggested as the indicator for the occurrence of non-small cell lung cancer whereas overexpression of HOXA9 can significantly repress the invasiveness of A549 and HCC95 cells." (PMID 29662084, 2018). "The effect of promoter methylation of the HOX family of genes in patients’ survival has not been reported previously, but promoter hypermethylation of HOXA9 in non-smokers is associated with recurrence-free survival (RFS) in non-small cell lung cancer." (PMID 33193605, 2020). "In addition, Esteller and the associates used methylation array to establish methylation profiles of stage I Caucasian non-small cell lung cancer and identified that methylation of two or more genes in HIST1H4F, PCDHGB6, NPBWR1, ALX1, and HOXA9 correlated with an increased risk of cancer recurrence." (PMID 27484806, 2016). "DNA methylation changes, especially hypermethylation of SOX1 and HOXA9, may serve as biomarkers for diagnosis and prognosis in non-small cell lung carcinoma (NSCLC)." (PMID 40699796, 2025). "In this context, our study aimed to evaluate the diagnostic performance of a panel of three genetic and epigenetic markers; HOXA9 gene promoter methylation, SOX2 and HV2 genes copy number variation in circulating cell free DNA in non-small cell lung cancer." (PMID 37038139, 2023). "A study including patients with late-stage, non-small cell, lung carcinoma (NSCLC) found meth-HOXA9 to be a negative prognostic factor at baseline with enhanced impact after the first treatment cycle." (PMID 36230519, 2022). "Although HOXA9 has been reported to regulate RELA expression in Non-small Cell Lung Cancer, no report has demonstrated such regulation is direct or indirect." (PMID 31683603, 2019). "In a model of non-small cell lung cancer (NSCLC), HOXA9 was downregulated in lung tumor tissues when compared with matched non-tumor tissues, and HOXA9 overexpression inhibited cell migration and invasion which is also associated with the regulation of NF-κB activity." (PMID 36376832, 2022).
acute leukemia (18 papers, 2010 to 2025). A clonal (malignant) hematopoietic disorder with an acute onset, affecting the bone marrow and the peripheral blood. "Aberrant HOXA9 expression is a hallmark of most aggressive acute leukemias, notably those with KMT2A (MLL) gene rearrangements." (PMID 33001025, 2020). "KMT2A activates cell proliferation via HOXA9, and MEIS1 upregulation and is therefore a major player in leukemogenesis: roughly every second acute leukemia is characterized by aberrantly increased HOXA9 expression." (PMID 39754404, 2025). "Trials have shown promising clinical activity of the selective SYK inhibitor entospletinib in patients with high expressing HOXA9/MEIS1 acute leukemias." (PMID 40188268, 2025). "Here, we perform genome-wide CRISPR/Cas9 screening in the HOXA9-driven reporter acute leukemia cells." (PMID 38216972, 2024). "Dysregulation of the homeobox (HOX)-containing transcription factor HOXA9 is a prominent feature in most aggressive acute leukemias." (PMID 33001025, 2020). "To date, most known HOXA9 regulator proteins are epigenetic modifiers, and little is known about which DNA-binding transcription factors are involved in directly regulating HOXA9 expression in acute leukemia." (PMID 33001025, 2020). "In this cohort study, 5 patients progressed to acute leukemia; of those, 3/5 expressed HOXA9 at diagnosis and developed AML, while the other 2, who developed ALL, did not express HOXA9." (PMID 24385825, 2013). "Regarding the patients that progressed to acute leukemia, the 3 that developed AML had HOXA9/ABL ratios of 0.31, 0.47, and 1.37 at diagnosis, while the other 2 who developed ALL did not express HOXA9." (PMID 24385825, 2013). "Lastly, although the clinical significance of HOXA9 has been recognized for more than two decades, it is technically difficult to systematically discover regulators of HOXA9 in acute leukemia owing to the lack of an endogenous reporter to dictate HOXA9 expression." (PMID 33001025, 2020). "In KMT2A-rearranged acute leukemia, sensitization following curaxin and panobinostat treatment is mediated by increasing histone acetylation, decreasing MYC expression, and not by altered expression of target genes HOXA9 and MEIS1." (PMID 37370721, 2023).
glioblastoma (18 papers, 2015 to 2025). The most malignant astrocytic tumor (WHO grade IV). "Moreover, HOXA9 has been implicated as an oncogene in glioblastoma and its aberrant expression seems to be independently predictive of shorter survival rates." (PMID 30961526, 2019). "Recently, our studies showed that HOXA9 overexpression is associated with poor prognosis in patients with glioblastoma (GBM), the most common and most malignant primary brain tumor." (PMID 26484224, 2015). "For example, the activation of HOXA9 is regarded as a novel, independent, and negatively prognostic marker in malignant glioblastoma (GBM) patients." (PMID 36376832, 2022). "In contrast, it was determined that HOXA9 promotes the viability and aggressiveness of glioblastoma cells." (PMID 31043660, 2019). "Functional studies with HOXA9-overexpressing and HOXA9-silenced glioblastoma cell models revealed that HOXA9 promotes cell viability, stemness and invasion, and inhibits apoptosis." (PMID 25762636, 2015). "The prognostic value of HOXA9 in glioblastoma patients was validated in two large datasets from TCGA and Rembrandt, where high HOXA9 levels were associated with shorter survival." (PMID 25762636, 2015). "Here we investigated the oncogenic potential of HOXA9 in gliomagenesis, the molecular and cellular mechanisms by which HOXA9 renders glioblastoma more aggressive, and how HOXA9 affects response to chemotherapy and survival." (PMID 25762636, 2015). "Given its prognostic value, a more complete understanding of the molecular targets and the functional consequences of HOXA9 activation on the establishment and maintenance of the malignant phenotype of glioblastoma is required." (PMID 25762636, 2015). "Furthermore, Homeobox protein Hox-A9 (HOXA9) was closely related with cisplatin resistance in bladder cancer, and HOXA9 modulated cancer stem cell properties in pancreatic cancer and glioblastoma." (PMID 32655321, 2020). "While HOXA9 was also previously shown to display pro-viability and anti-apoptotic functions in glioblastoma in vitro, the downstream functional consequences of HOXA9 activation have remained unknown." (PMID 25762636, 2015). "Together, these findings suggest that LDHA-directed ERK pathway regulates HOXA9, YAP1, and STAT3 transcription factors and/or signaling pathways in glioblastoma cells and GSCs." (PMID 38443336, 2024). "The concomitant expression of HOXA9 and WNT6 results in overactivation of the WNT/β‐catenin signaling pathway in vitro and in vivo, and identifies a subgroup of glioblastoma patients with particularly dismal prognosis, suggesting this HOXA9‐WNT6 link may be an attractive therapeutic target." (PMID 31923345, 2020). "Several reports have suggested that high expression of homeotic genes, including HOXA9, HOXA13, mesenchyme HOX2 (MEOX2), and HOXD4 is an indicator of poor prognosis in glioblastoma (GBM) patients." (PMID 34458259, 2021). "Additionally, several studies have reported that HOXA9 and HOXA10 can serve as predictive biomarkers of poor survival in glioblastoma multiforme (GBM)." (PMID 32296636, 2020).
pancreatic cancer (17 papers, 2010 to 2024). "The role of HOXA9 requires further investigations in pancreatic cancer as HOXA9 inhibitors are being developed." (PMID 39462379, 2024). "This has been observed with miR-210, which was found to target HOXA9 in pancreatic cancers, although for prostate cancers that target was determined to be the neural cell adhesion molecule (NCAM)." (PMID 34680611, 2021). "HOTTIP is antisense to HOXA13 and modulates cancer stem cell properties in human pancreatic cancer by regulating HOXA9." (PMID 31890219, 2019). "The long non-coding RNA, HOTTIP, binds with WD repeat-containing protein 5 to enhance HoxA9 expression, which, in turn, activates the Wnt/β-catenin pathway in pancreatic cancer cells to promote stemness properties." (PMID 31137902, 2019). "WDR5 has been shown to cooperate with HOTTIP to promote HOXA9 in prostate and pancreatic cancer and HOXA13 expression in esophageal and gastric cancer cells by increasing H3K4Me3 on their promoters." (PMID 29925347, 2018). "Most of the genes in the verification data are functionally cancer related including the genes showing sex difference Both genes CASP6 and HOXA9 are hypermethylated, leading to decreased gene expression in pancreas cancer tissue." (PMID 20386599, 2010). "HOTTIP could maintain the stemness of cancer stem cells (PCSCs) through the HOTTIP/WDR5/HOXA9/Wnt axis in pancreatic cancer; lncRNA H19 mediated the methotrexate resistance in colorectal cancer through activating Wnt/β-catenin signaling." (PMID 34690755, 2021). "A role for HoxA9 in the self-renewal of cancer cells has been suggested in pancreatic cancer." (PMID 31137902, 2019). "In addition, HOTTIP can also mediate HOXA9 to enhance the stemness of pancreatic cancer cells." (PMID 32307830, 2020). "Therefore, HOXA9 might enhance pancreatic cancer development." (PMID 39462379, 2024). "Its impact on downstream target genes like E2F3, EFNA3, GIT2, MNT, ZNF462, HOXA9, and EGR3 underscores its significance in shaping the aggressive phenotype of pancreatic cancer cells." (PMID 38132457, 2023). "The data from this study collectively showed that under hypoxic conditions, miR-210 suppressed levels of HOXA9 to activate the NFκB pathway, which drives EMT in pancreatic cancer." (PMID 34680611, 2021). "MiR‐210 inhibits the expression of HOXA9 to activate the NF‐κB signaling, induces EMT, and reduces the sensitivity of pancreatic cancer cells to gemcitabine induced by HIF1A under hypoxia." (PMID 33939301, 2021). "The upregulation of HOTTIP/HOXA9 enhances the Wnt/β-catenin signaling pathway, whereas silencing of HOTTIP/HOXA9 reduces the expression of the Wnt protein family (Wnt1, Wnt3a, Wnt10a, and Wnt110b) in pancreatic cancer." (PMID 35819532, 2022). "In pancreatic cancer cells, HOTTIP regulates HOXA10, HOXB2, HOXA11, HOXA9 and HOXA1, but not HOXA13." (PMID 30819158, 2019). "However, another study in pancreatic cancer cells demonstrated that HOTTIP did not modulate HOXA13 expression, but did regulate the expression of other HOX genes such as HOXA1, HOXA9, HOXA10, HOXA11 and HOXB2." (PMID 28938659, 2017).